ACVR1 (activin A receptor type 1)
Description:
Bone morphogenetic protein (BMP) type I receptor that is involved in a wide variety of biological processes, including bone, heart, cartilage, nervous, and reproductive system development and regulation. As a type I receptor, forms heterotetrameric receptor complexes with the type II receptors AMHR2, ACVR2A or ACVR2B. Upon binding of ligands such as BMP7 or GDF2/BMP9 to the heteromeric complexes, type II receptors transphosphorylate ACVR1 intracellular domain. In turn, ACVR1 kinase domain is activated and subsequently phosphorylates SMAD1/5/8 proteins that transduce the signal. In addition to its role in mediating BMP pathway-specific signaling, suppresses TGFbeta/activin pathway signaling by interfering with the binding of activin to its type II receptor. Besides canonical SMAD signaling, can activate non-canonical pathways such as p38 mitogen-activated protein kinases/MAPKs (By similarity). May promote the expression of HAMP, potentially via its interaction with BMP6 (By similarity).
Synonyms: SKR1; ACVRLK2; ALK2; ACVR1A; ACTRI; FOP; TSRI
Tractability: Small molecule: a structure with a bound ligand is known; a high-quality ligand is known; it has a high-quality binding pocket; it belongs to a druggable protein family. Antibody: its Gene Ontology location is reachable by antibodies, with high confidence; UniProt predicts a signal peptide or a membrane-spanning region. PROTAC: ubiquitination databases record sites on it; its protein half-life has been measured; a small molecule that binds it is known. Other modalities: an approved drug acts on it.
Target class: TKL protein kinase group; TKL protein kinase STKR1; TKL protein kinase STKR family; Protein Kinase; Enzyme; Kinase
Chemical probes: M4K2149 (high quality), M4K2234 (high quality), ML347, MU1700 (high quality), fidrisertib
Gene: Protein-coding gene on chromosome 2 (157,736,249 to 157,876,347, reverse strand). Ensembl gene ENSG00000115170.
Subcellular location: Membrane
Gene Ontology:
Molecular function: activin binding; activin receptor activity, type I; ATP binding; BMP receptor activity; cadherin binding; protein binding; protein homodimerization activity; protein kinase activity; protein serine/threonine kinase activity; protein tyrosine kinase binding; SMAD binding; transforming growth factor beta binding; transmembrane receptor protein serine/threonine kinase activity; peptide hormone binding; transforming growth factor beta receptor activity, type I; growth factor binding
Biological process: activin receptor signaling pathway; atrial septum primum morphogenesis; BMP signaling pathway; cardiac muscle cell fate commitment; cellular response to BMP stimulus; embryonic heart tube morphogenesis; endocardial cushion cell fate commitment; mitral valve morphogenesis; negative regulation of activin receptor signaling pathway; negative regulation of extrinsic apoptotic signaling pathway; negative regulation of G1/S transition of mitotic cell cycle; negative regulation of signal transduction; osteoblast differentiation; positive regulation of bone mineralization; positive regulation of cell migration; positive regulation of determination of dorsal identity; positive regulation of DNA-templated transcription; positive regulation of intracellular signal transduction; positive regulation of osteoblast differentiation; positive regulation of SMAD protein signal transduction; positive regulation of transcription by RNA polymerase II; regulation of ossification; transforming growth factor beta receptor signaling pathway; atrioventricular valve morphogenesis; cell differentiation; and 17 more
Cellular component: activin receptor complex; plasma membrane; BMP receptor complex; apical part of cell; membrane; receptor complex
Genetic constraint (gnomAD): Loss-of-function variants: 38 observed, 59.67 expected, observed/expected ratio (o/e) 0.64, 90% interval 0.49 to 0.83. The upper end of that interval is the gene's LOEUF score, 0.83, which puts it in group 3 of 6, group 1 being the genes least tolerant of losing a copy. Missense variants: 463 observed, 672.88 expected, observed/expected ratio (o/e) 0.69, 90% interval 0.64 to 0.74. Synonymous variants: 212 observed, 241.18 expected, observed/expected ratio (o/e) 0.88, 90% interval 0.79 to 0.99.
Gene-disease validity (ClinGen):
ClinGen rates the evidence that ACVR1 causes each of these diseases.
fibrodysplasia ossificans progressiva (autosomal dominant): Definitive. Fibrodysplasia ossificans progressiva (FOP) is a severely disabling heritable disorder of connective tissue characterized by congenital malformations of the great toes and progressive heterotopic ossification that forms qualitatively normal bone in characteristic extraskeletal sites.
congenital heart disease (autosomal dominant): Limited. A heart disease that is present at birth.
Cancer hallmarks: proliferative signalling (promotes); escaping programmed cell death (promotes); invasion and metastasis (promotes)
Homologues: Orthologues: macaque ACVR1 (99% identical), pig ACVR1 (99% identical), dog ACVR1 (99% identical), rabbit ACVR1 (99% identical), guinea pig ACVR1 (99% identical), mouse Acvr1 (98% identical), rat Acvr1 (97% identical), chimpanzee ACVR1 (96% identical), tropical clawed frog acvr1 (82% identical), Drosophila melanogaster babo (47% identical), Drosophila melanogaster tkv (43% identical), Caenorhabditis elegans sma-6 (35% identical), and 3 more. Paralogues in human: ACVRL1 (59% identical), ACVR1B (48% identical), BMPR1B (47% identical), ACVR1C (47% identical), TGFBR1 (47% identical), BMPR1A (46% identical), BMPR2 (28% identical), ACVR2A (28% identical), TGFBR2 (28% identical), ACVR2B (27% identical), AMHR2 (25% identical).
Diseases named in the same sentence as ACVR1 in open-access papers:
ACVR1 is named in the same sentence as 139 diseases in open-access papers, as found by Europe PMC text mining. Sharing a sentence is not in itself a finding about the gene and the disease. The quoted sentences say what the papers report.
fibrodysplasia ossificans progressiva (144 papers, 2009 to 2026). "Fibrodysplasia ossificans progressiva (FOP) is a rare genetic disease caused by a gain-of-function mutation in ACVR1, which is a bone morphogenetic protein (BMP) type I receptor." (PMID 38500216, 2024). "Fibrodysplasia ossificans progressiva (FOP) is a rare but destructive form of hereditary HO that is caused by ACVR1 mutations, which activate the bone morphogenetic protein (BMP) signaling pathway and subsequent ossification." (PMID 39286484, 2024). "Fibrodysplasia ossificans progressiva is caused by ACVR1 gene mutations, while progressive osseous heteroplasia is caused by GNAS gene mutations." (PMID 39620561, 2024). "Fibrodysplasia ossificans progressiva (FOP) is a genetic connective tissue disease in which mutations in ACVR1, encoding ALK2, make activin A switch from a competitor of signaling (e.g. NSC) to an agonist." (PMID 36717825, 2023). "Mutations in the ACVR1 gene are known to cause fibrodysplasia ossificans progressiva (FOP), a genetic disease characterized by progressive heterotopic ossification." (PMID 32641001, 2020). "Fibrodysplasia ossificans progressiva results in heterotopic ossification of muscle and connective tissue, a phenotype caused by dominant mutations in the gene ACVR1, encoding the activin A receptor 1 (OMIM 135100)." (PMID 32422592, 2020). "Fibrodysplasia ossificans progressiva (FOP) is a rare human skeletal disease caused by constitutively activating mutations in the gene ACVR1." (PMID 31828085, 2019). "ACVR1 gain‐of‐function mutations can cause the rare disease fibrodysplasia ossificans progressiva (FOP), where patients develop ectopic bone replacing soft tissue, tendons and ligaments." (PMID 30854720, 2019). "Fibrodysplasia ossificans progressiva is a severe disorder characterized by heterotopic ossification, and is caused by mutations in ACVR1." (PMID 29396429, 2018). "A mutation in ACVR1 (ALK2) is causative of fibrodysplasia ossificans progressiva, a disease that progresses with heterotopic ossifications in muscles, tendons, ligaments and general connective tissues." (PMID 27871224, 2016). "PLEKHB1 protein interacts with ACVR1, which is involved in fibrodysplasia ossificans progressiva (FOP), a rare congenital disorder that causes bone formation in muscles, tendons, ligaments, and connective tissues." (PMID 27325353, 2016). "Fibrodysplasia ossificans progressiva is a rare autosomal dominantly inherited disorder of connective tissue caused by mutations in the gene encoding for ACVR1/ALK2, a bone morphogenetic protein type I receptor." (PMID 26966495, 2015). "A point mutation in ACVR1 can cause fibrodysplasia ossificans progressiva (FOP) in which ectopic ossification occurs in skeletal muscles and deep connective tissues." (PMID 22934054, 2012). "In addition, Ddr2 deficiency attenuates HO in mice expressing the ACVR1 mutation associated with human fibrodysplasia ossificans progressiva." (PMID 39746922, 2025). "Fibrodysplasia Ossificans Progressiva and Epicanthus are two diseases linked to ACVR1." (PMID 36993785, 2023). "Moreover, ACVR1 has been extensively studied for its causal role in fibrodysplasia ossificans progressiva (FOP), a rare genetic disorder characterised by progressive heterotopic ossification." (PMID 31683698, 2019). "In related studies, others showed that small molecule antagonists of BMP signaling inhibited ectopic cartilage and bone formation in mouse models of the severe pediatric disorder Fibrodysplasia Ossificans Progressiva (FOP) that is caused by activating mutations in the type I BMP receptor ACVR1/ALK2." (PMID 28445472, 2017).
fibrodysplasia ossificans progressiva (continued). "One such genetic disease is fibrodysplasia ossificans progressiva (FOP), a rare disorder driven by activating mutations in the ACVR1 gene." (PMID 39677926, 2025). "The most devastating in terms of HO severity is fibrodysplasia ossificans progressiva (FOP), which has been shown to be caused by mutations in the gene encoding activin A receptor type 1 (ACVR1)." (PMID 38948860, 2024). "Classic fibrodysplasia ossificans progressiva (FOP) is an extremely rare congenital disorder caused by a recurrent gain-of-function point mutation (R206H) in the Activin receptor A type I (ACVR1, also known as ALK2) gene." (PMID 38397384, 2024). "Fibrodysplasia ossificans progressiva (FOP) is a rare congenital disorder characterized by abnormal bone formation due to ACVR1 gene mutations." (PMID 38540766, 2024). "Fibrodysplasia ossificans progressiva (FOP) is an extremely rare connective tissue disease associated with mutations in the activin A receptor type 1 gene." (PMID 38485853, 2024). "Fibrodysplasia ossificans progressiva (FOP), also known as Stoneman syndrome, is a rare genetic disorder characterized by abnormal bone development caused by activating mutations of the ACVR1 gene." (PMID 37521595, 2023). "Fibrodysplasia ossificans progressiva (FOP) is a catastrophic, ultra-rare disease of heterotopic ossification caused by genetic defects in the ACVR1 gene." (PMID 36768622, 2023). "Fibrodysplasia ossificans progressiva (FOP) is a rare autosomal genetic disease caused by dominant gain-of-function mutations in the coding sequence of the ACVR1 gene, encoding the activin A receptor type 1, a bone morphogenetic protein (BMP) type I receptor." (PMID 35567665, 2022). "Fibrodysplasia ossificans progressiva (FOP) is an ultra-rare genetic condition caused by mutations in the ACVR1/ALK2 gene that affects approximately 1 in 2 million people worldwide." (PMID 36439163, 2022). "In humans, loss of function mutations in the ACVR1 gene result in congenital cardiac defects affecting the valve and septum formation, while gain of function mutations lead to the rare but fatal fibrodysplasia ossificans progressiva (FOP) disease, characterized by aberrant heterotopic ossification." (PMID 36005436, 2022). "Around half of ACVR1 mutations were R206H and G356D, gain-of-function mutations commonly found in fibrodysplasia ossificans progressiva (FOP) and diffuse intrinsic pontine gliomas (DIPGs)." (PMID 34360647, 2021). "Hereditary HO, also known as fibrodysplasia ossificans progressiva (FOP), is a rare autosomal dominant disease resulting from activin A receptor type I (ACVR1) gene mutation." (PMID 32853465, 2020). "Fibrodysplasia ossificans progressiva (FOP) is an ultra-rare disease of massive heterotopic ossification caused by a highly recurrent R206H mutation in ACVR1/ALK2." (PMID 32727600, 2020). "Focusing on the ligand-independent constitutive activation of mutated ACVR1 in fibrodysplasia ossificans progressiva (FOP) patients, Ikeya and colleagues have identified two hit compounds that were effective in multiple FOP model mice." (PMID 30392977, 2018). "Activating mutations in ACVR1 are responsible for fibrodysplasia ossificans progressiva (FOP), a rare disease characterized by congenital toe malformation and progressive heterotopic endochondral ossification leading to severe and cumulative disability." (PMID 27125279, 2016). "The mutated amino acid residues in ACVR1, which encodes a serine threonine kinase, ALK2, have previously been reported as germline mutations causing fibrodysplasia ossificans progressiva (FOP), an inherited musculoskeletal disease." (PMID 25077668, 2014).
fibrodysplasia ossificans progressiva (continued). "Fibrodysplasia ossificans progressiva (FOP): FOP is a rare genetic disorder caused by hyperactive mutations in the bone morphogenetic protein (BMP) type I receptor ACVR1." (PMID 25621177, 2014). "Involved in ossification of muscles and joints in fibrodysplasia ossificans progressiva (FOP) disease, through mutations in ACVR1 and noggin gene." (PMID 22934054, 2012). "Heterozygous mutations in the Bone morphogenetic protein (BMP) type I receptor ACVR1, encoding activin-like kinase 2 (ALK2), underlie all cases of the rare genetic musculoskeletal disorder Fibrodysplasia Ossificans Progressiva (FOP)." (PMID 40121219, 2025). "In fibrodysplasia ossificans progressiva (FOP), a rare genetic disease characterized by progressive and systemic HO, the Activin A/mutated ACVR1/mTORC1 cascade induces HO in progenitors in muscle tissues." (PMID 38365425, 2024). "Fibrodysplasia ossificans progressiva (FOP), the most devastating genetic condition of HO, is due to mutations in the ACVR1/ALK2 gene and is relentlessly progressive." (PMID 38672501, 2024). "Fibrodysplasia ossificans progressiva (FOP), an exceptionally rare genetic disorder, is attributable to mutations in the ACVR1/ALK2 gene, leading to progressive heterotopic ossification." (PMID 38530400, 2024). "Fibrodysplasia ossificans progressiva (FOP; MIM# 135100) is an ultra-rare congenital disorder caused by gain-of-function point mutations in the Activin receptor A type I (ACVR1, also known as ALK2) gene." (PMID 38397384, 2024). "Fibrodysplasia ossificans progressiva (FOP) is a rare genetic disorder characterized by the gradual heterotopic ossification of soft tissues, leading to abnormal bone growth within muscles, tendons, and ligaments, due to a mutation in the ACVR1 gene." (PMID 37700978, 2023). "Fibrodysplasia ossificans progressiva (FOP) is a very rare, severe genetic disorder triggered by a gain-of-function mutation in the ACVR1 gene that codes for the type I bone morphogenetic protein (BMP) receptor ACVR1 (activin A receptor—type 1), also known as ALK2 (activin receptor-like kinase-2)." (PMID 37603129, 2023). "An ALK2/BMP type 1 receptor kinase inhibitor has been studied in pre-clinical models for other disease processes (i.e., fibrodysplasia ossificans progressiva) associated with ACVR1 with good results." (PMID 35629262, 2022). "Acvr1 is changed in patients with fibrodysplasia ossificans progressiva, accompanied by cognitive decline, sensory abnormality, and cerebellar abnormality." (PMID 36614117, 2022). "Unfortunately, this pathological phenomenon is also observed in a rare genetic disorder known as fibrodysplasia ossificans progressiva (FOP), which is caused by a gain-of-function mutation in the bone morphogenetic protein (BMP) type I receptor ACVR1." (PMID 33644068, 2021). "Such an approach was taken to study fibrodysplasia ossificans progressiva (FOP), which is a disease of heterotopic ossification caused by activating mutation in activin A type I receptor (ACVR1)." (PMID 33260307, 2020). "Fibrodysplasia ossificans progressiva (FOP) is an extremely rare condition in which muscle and other soft tissues are spontaneously transformed into bone, and it is caused by a specific activating mutation in Acvr1." (PMID 32053985, 2020). "However, identical ACVR1 mutations are found in the germline in individuals with the monogenic developmental disorder fibrodysplasia ossificans progressiva (FOP), characterised by skeletal abnormalities and disabling heterotopic ossification." (PMID 31551357, 2019). "Mutations in the ACVR1/ALK2 gene lead to hyper-activation of ACVR1/ALK2 signaling in the genetic disease fibrodysplasia ossificans progressiva (FOP) and in pediatric pontine glioma." (PMID 26701726, 2016).